HP (haptoglobin)
Diseases named in the same sentence as HP in open-access papers (continued):
Sharing a sentence is not in itself a finding about the gene and the disease.
viral infection (11 papers, 2014 to 2025). "It is noteworthy that many studies of APPs in viral infections have identified the participation of SAA and HP." (PMID 37111415, 2023). "In the most common ruminant viral diseases, elevated serum amyloid A (SAA) and haptoglobin (Hp) levels in blood serum have been observed." (PMID 30223561, 2018). "Haptoglobin (HP) and serum amyloid A (SAA) have been shown to play a role in viral infections such as caprine arthritis encephalitis, border disease, sheep and goat plague, bluetongue, bovine viral diarrhea, foot-and-mouth disease, and bovine respiratory syncytial virus (BRSV)." (PMID 37111415, 2023).
autoimmune hemolytic anemia (10 papers, 2013 to 2026). Autoimmune hemolytic anemia (AIHA) is an autoimmune disorder in which various types of auto-antibodies are directed against red blood cells causing their survival to be shortened and resulting in hemolytic anemia. "The rupture of red blood cells caused by SLE-associated autoimmune hemolytic anemia and glomerular injury are the main sources of haptoglobin–hemoglobin complexes." (PMID 37583695, 2023). "Initial blood tests showed hemoglobin of 6.1 g/dl, reticulocytes count of 19.7%, total bilirubin of 3.2 mg/dl, lactate dehydrogenase of 600 U/L, and haptoglobin of less than 8 mg/dl, and direct Coombs test was positive for warm immunoglobulin G. The impression was autoimmune hemolytic anemia (AIHA)." (PMID 29130008, 2017). "Six patients presented a decrease in haptoglobin without clinical evidence of autoimmune hemolytic anemia or increases in plasma bilirubin and lactate dehydrogenase." (PMID 29108368, 2017).
Cognitive impairment (10 papers, 2018 to 2026). Abnormal cognition is characterized by deficits in thinking, reasoning, or remembering. "Previous studies found increased plasma and brain haptoglobin levels in AD patients compared to controls and an association between haptoglobin levels and the severity of cognitive impairment." (PMID 35769604, 2022). "We identified liver‐derived blood proteins C3, HP, ITIH4, and SAA1 as the candidate molecules associated with cognitive impairment based on the proteomics of mouse liver and blood, as well as the transcriptomic and proteomic profiles of human organs." (PMID 41221556, 2026). "In this line, there are only two studies relating HP levels to AD severity by showing significantly higher serum levels of HP in AD, and mild cognitive impairment compared to healthy subjects." (PMID 35203598, 2022). "Additionally, a significant positive correlation between the serum HP level and the severity of cognitive impairment was observed in patients with AD." (PMID 38192726, 2023). "Furthermore, the serum levels of ANG-2, VEGFA, haptoglobin, and p-Tau181 were correlated with cognitive impairment." (PMID 35769604, 2022). "We observed a significant positive association between HPX and haptoglobin and a trend for Hbβ and Hbδ, only in CN individuals who remained stable, but this association was absent in those that progressed to cognitive impairment." (PMID 32517787, 2020). "In our dataset, higher levels of haptoglobin were associated with increased levels of CD163 in stable CN individuals but demonstrated a trend of negative association in those showing progression to cognitive impairment." (PMID 32517787, 2020).
depression (10 papers, 2012 to 2025). "Conventional analytical methods also verify the existence of higher plasma haptoglobin levels in FMS and associate them with symptoms of depression, hyperalgesia, exhaustion, and sleep disturbances." (PMID 38652420, 2024). "Then, we measured the concentrations of ALOX15B (also known as Alox8 in mice), RPLP0 and HP in our depression mouse model." (PMID 37942417, 2023). "Haptoglobin has also been reported to be elevated in depression and to differentiate between depressive subtypes." (PMID 33255237, 2020). "In this context, there is abundant evidence that clinical depression is an immuno-inflammatory disorder characterized by among other things increased levels of PICs and acute phase proteins, including C-reactive protein and haptoglobin." (PMID 22747645, 2012). "For example, melancholia is characterized by increased levels of acute phase proteins, e.g., haptoglobin, expression of T cell activation markers and increased resistance of IL-1β and sIL-2R production to dexamethasone administration as compared to simple major depression." (PMID 29103192, 2018). "It has been reported that elevated amounts of the proteins haptoglobin (HP) and alpha-1-antichymotrypsin (SERPINA3) highly correlate with each other and with the severity of depression and negatively correlate with the thyroid-stimulating hormone response to thyrotropin." (PMID 39062058, 2024).
periodontitis (10 papers, 2016 to 2025). An acute or chronic inflammatory process that affects the tissues that surround and support the teeth. "Additionally, chronic periodontitis is associated with elevated systemic levels of other pro-inflammatory mediators, such as fibrinogen, haptoglobin, and IL-18, alongside decreased anti-inflammatory markers like IL-4." (PMID 40136726, 2025). "Higher levels of Haptoglobin were associated with host defense in periodontitis cases." (PMID 37408223, 2023). "Despite these circumstances, a common protein, haptoglobin, was found in these studies to have a similar pattern of expression; it was significantly increased in active periodontitis compared to post-treatment." (PMID 37834046, 2023). "To date, only one study has evaluated genotype and allele frequencies of HP and NRAMP1 polymorphisms in patients with periodontitis and peri-implantitis." (PMID 35919305, 2020). "Within the limitations of this study, it seems that there is a relationship between HP and NRAMP1 allele frequencies and the presence of heme-consuming periodontal pathogens in the Iranian patients with chronic periodontitis and peri-implantitis." (PMID 35919305, 2020). "A classical study had already found higher levels of Haptoglobin in periodontitis cases." (PMID 36355174, 2022). "Within the limitations of this study, it seems that there was a relationship between HP and NRAMP1 allele frequencies and the presence of heme-consuming periodontal pathogens in the Iranian patients with chronic periodontitis and peri-implantitis evaluated in the present study." (PMID 35919305, 2020). "The remaining 34 proteins showed at least 2-fold higher expression in periodontitis, highlighting immunoglobulins (Ig) heavy constant gamma 3 (3.78), kappa light chain (2.19), and heavy variable 5-51 (2.18), plasma protease C1 inhibitor (3.61), haptoglobin (3.35), and another Hb, delta (3.26)." (PMID 40384977, 2025). "This study aimed to assess the association of haptoglobin (HP) and natural resistance-associated macrophage protein 1 (NRAMP1) alleles with the presence of heme-consuming periodontal pathogens in a group of Iranian patients with chronic periodontitis and peri-implantitis." (PMID 35919305, 2020). "Therefore, the authors hypothesized that the up-regulation of haptoglobin derived fragment levels in chronic periodontitis patients compared to healthy subjects may reflect the anti-inflammatory and reestablishment process of the periodontium." (PMID 32722327, 2020). "In agreement with our results, others proteomic studies evidenced an overexpression of HP in the GCF obtained from periodontal disease and aggressive periodontitis." (PMID 35329612, 2022). "Considering that Langerhans cells in the epithelium can also synthesize Haptoglobin, its levels may be in increased expression in local or systemic inflammation, justifying our results related to the higher levels of this protein in obese women with periodontitis." (PMID 36355174, 2022). "Among these, only the peak at m/z 3434.4 was successfully identified to be derived from haptoglobin by nano-LC/ESI-MS/MS analysis and its upregulation in chronic periodontitis patients was confirmed also for saliva samples." (PMID 32722327, 2020). "In the present study, we found that HP, KNG1, A1AT and IGKC were differentially expressed in sera collected from periodontal patients." (PMID 27635317, 2016).
Alzheimer disease (9 papers, 2011 to 2025). A progressive, neurodegenerative disease characterized by loss of function and death of nerve cells in several areas of the brain leading to loss of cognitive function such as memory and language. "It has been found that the up‐regulation of haptoglobin expression is associated with blood‐brain barrier dysfunction, which causes various pathological conditions, including Alzheimer's disease (AD), Parkinson's disease (PD), and Huntington's disease (HD)." (PMID 34018701, 2021). "Stimuli for this release of the processed haptoglobin include amyloid-β peptides in Alzheimer’s disease, signals secreted in the surrounding of glial tumors, or supposedly elevated zonulin levels." (PMID 39200114, 2024). "Polymorphic changes in several genes such as Cryptochrome Circadian Regulator 1 (CRYL1), ApoE and haptoglobin (HP) have been described in patients with Alzheimer’s disease." (PMID 31052559, 2019). "Some studies show increased levels of haptoglobin was found in CSF from patients with Alzheimer’s disease (AD), Parkinson’ disease (PD) and Huntington’s disease (HD)." (PMID 28966798, 2017). "APOE, HP, and CRYL1 have all been associated with Alzheimer’s Disease, the pathology of which involves lipid and cholesterol pathways." (PMID 28206976, 2017). "Moreover, the genetic instrument for CSF haptoglobin was derived from a relatively small, European ancestry cohort, which included individuals with Alzheimer's disease." (PMID 40763130, 2025). "Additionally, elevated CSF haptoglobin levels have be seen in idiopathic normal pressure hydrocephalus, traumatic brain injury, Alzheimer's disease, multiple sclerosis, neuromyelitis optica, and Guillain-Barré syndrome, and therefore may not be specific to HD." (PMID 21297956, 2011).
bladder cancer (9 papers, 2011 to 2023). "Our finding is consistent with previous ones reporting elevated haptoglobin levels in Turkish and Polish bladder cancer patients." (PMID 32620920, 2020). "Among the three validated proteins, haptoglobin was able to distinguish between patients with low grade bladder cancer and the controls with high sensitivity and specificity (AUC > 0.87)." (PMID 32620920, 2020). "Haptoglobin level was significantly increased (p = 0.0006) in low grade bladder cancer patients when compared to healthy control group." (PMID 32620920, 2020). "With reasonable specificity and sensitivity (AUC > 0.87), haptoglobin could differentiate between patients with low-grade bladder cancer and controls." (PMID 38202898, 2023). "Interestingly, haptoglobin effectively differentiated low-grade bladder cancer patients from controls with high accuracy (AUC > 0.87), suggesting its potential as a biomarker for early bladder cancer detection, pending further validation." (PMID 38201450, 2023). "The amount of haptoglobin was found to be significantly higher in patients with low-grade bladder cancer, suggesting that this protein may have a role in the initial stages of bladder tumorigenesis." (PMID 38202898, 2023). "Haptoglobin is a potential candidate that merit further investigation to validate its usefulness and functional significance as potential biomarkers for early detection of bladder cancer." (PMID 32620920, 2020). "Some of the proteins such as SERPINA1, FGG, FGA, APOA1 and HP were also found with differential abundance in urine in proteomics studies of bladder cancer, and TYMP in tissue in renal cell carcinoma, but mostly with opposite abundance level compared to our study." (PMID 25653573, 2015). "We observed increased expression of five proteins, including fibrinogen (Fb), lactate dehydrogenase B (LDHB), apolipoprotein-A1 (Apo-A1), clusterin (CLU) and haptoglobin (Hp), which were increased in urine samples of patients with low malignant or aggressive bladder cancer." (PMID 21496341, 2011). "However, no study has been conducted on the association between the HP genotypes and bladder cancer." (PMID 32256273, 2020). "The level of haptoglobin was found to be highly elevated in low grade NMIBC patients, which point to the potential involvement of this protein in early stages of bladder cancer development." (PMID 32620920, 2020). "HP-NAP has also been shown to be a novel therapeutic agent for the treatment of allergic asthma and bladder cancer." (PMID 23577158, 2013).
fibrosis (9 papers, 2007 to 2025). the formation of excess fibrous connective tissue in an organ or tissue in a reparative or reactive process. "Only one patient (1/160 = 0.6%) had a repeated FT suggesting advanced fibrosis (FT = 0.49), with a high-risk profile of false positive (hemolysis suspected with haptoglobin = 0.24 g/L and unconjugated bilirubin = 32 microm/L)." (PMID 18596917, 2008). "Seven individual protein spots were identified as either significantly increased (α2-macroglobulin, haptoglobin, albumin) or decreased (complement C-4, serum retinol binding protein, apolipoprotein A-1, and two isoforms of apolipoprotein A-IV) with advanced fibrosis." (PMID 17625010, 2007).
melanoma (9 papers, 1980 to 2025). A malignant, usually aggressive tumor composed of atypical, neoplastic melanocytes. "We have previously identified constitutive DAMPs (HMGB1 and Calreticulin) as well as new putative inducible DAMPs such as Haptoglobin (HP), from a therapeutically used heat shock-conditioned melanoma cell lysate (called TRIMEL)." (PMID 35805888, 2022). "One of the main overexpressed proteins by HS conditioning of the melanoma cells belonging the lysate TRIMEL was HP, a plasmatic glycoprotein with a molecular weight of 38 kDa." (PMID 29744371, 2018). "Single serum samples from 59 melanoma patients and age- and sex-matched controls were further examined for sialic acid, alpha 1-acid glycoprotein, alpha 1-antitrypsin, haptoglobin, and alpha 2-macroglobulin." (PMID 6158966, 1980).
parasitemia (9 papers, 2014 to 2026). "Increased haptoglobin in wildlife may reflect ongoing parasitic infection, association with environmental pollutants in marine mammals, and has been proposed as a marker for population health in non-domestic animal populations." (PMID 31998761, 2019). "G6PD deficiency, length of illness, and reticulocyte count changes were inversely related and the day 0 parasitemia level directly related to changes in the haptoglobin level." (PMID 31549159, 2019). "Haptoglobin is known to increase several fold during an inflammatory event and the levels (e.g. high or low of haptoglobin subtypes) of haptoglobin has an important role in the disease development for other parasitic diseases in regards to exacterbated oxidative stress." (PMID 35902827, 2022). "Interestingly, some of the proteins such as SAA, HP, Apo E and Apo A1 exhibited sequential alterations in their serum abundances with the increase in parasitemia." (PMID 28667326, 2017). "Results from clinical studies have shown that HP gene polymorphisms can exert various effects on the course of bacterial, viral, and parasitic infections, as well as noninfectious diseases, affecting the severity and progression of the pathology." (PMID 25147423, 2014). "Laboratory evaluation demonstrated hemoglobin decline, indirect hyperbilirubinemia, elevated lactate dehydrogenase (LDH), reticulocytosis, low haptoglobin, and absence of parasitemia - confirming PADH." (PMID 41835667, 2026).
pneumonia (9 papers, 2013 to 2025). An acute, acute and chronic, or chronic inflammation focally or diffusely affecting the lung parenchyma, caused by an infection in one or both of the lungs (by bacteria, viruses, fungi, or mycoplasma.). "It was also known that in severe pneumonia the haptoglobin increase was associated to the apolipoprotein-A1 decrease, as we observed in the cohorts with high prevalence of severe Covid-19." (PMID 33216772, 2020). "Haptoglobin was in the reference interval (1.42 g/L and 1.86 g/L) in the two dogs with pneumonia, as well as in the other IR dogs, as was 25(OH)D." (PMID 39409857, 2024). "In this study, we observed that RNA levels of genes encoding for the expression of ferritin, ceruloplasmin, lactoferrin and haptoglobin are increased 4 to 20 fold during P. aeruginosa acute pneumonia." (PMID 27982111, 2016). "Secondly, the concentration of plasma haptoglobin increased with disease severity in patients with Pneumonia." (PMID 24696240, 2014). "In patients with severe pneumonia, apolipoprotein-A1 decrease was associated with acute inflammation and the “cytokine storm” with an increase in IL6 and acute phase proteins such as CRP and haptoglobin." (PMID 33216772, 2020).
subarachnoid hemorrhage (9 papers, 2012 to 2024). A serious neurological disorder characterized by intracranial hemorrhage into the subarachnoid space. "Haptoglobin is the body’s first line of defence against the toxicity of extracellular haemoglobin released following a subarachnoid haemorrhage (SAH)." (PMID 38069244, 2023). "Demographic and clinical characteristics of patients with subarachnoid hemorrhage according to haptoglobin (Hp) phenotype." (PMID 35386117, 2022). "Exogenously added haptoglobin bound most uncomplexed haemoglobin, in the first 2 weeks after human subarachnoid haemorrhage, indicating a wide therapeutic window." (PMID 32346673, 2020). "We review the relevance of haptoglobin in subarachnoid hemorrhage and discuss the effects of genotype and expression levels on the known mechanisms of early brain injury (EBI) and cerebral ischemia after aneurysm rupture." (PMID 29904350, 2018). "Hemopexin and haptoglobin concentrations were nearly negligible in the brainafter intracerebral and subarachnoid hemorrhage." (PMID 29742229, 2018). "Interestingly, haptoglobin genotype affected functional outcomes in humans after subarachnoid hemorrhage —haptoglobins provide important CSF heme scavenging." (PMID 35880253, 2022). "After subarachnoid hemorrhage, the intrathecal CD163-haptoglobin–hemoglobin system was saturated, as shown by the presence of extracellular hemoglobin despite detectable haptoglobin." (PMID 22380637, 2012). "This suggests that hemoglobin detoxification from the subarachnoid space after subarachnoid hemorrhage is not carried out only by resident macrophages (ED2+) and their CD163 mediated haptoglobin-hemoglobin uptake, but also via phagocytosis by activated (ED1+) macrophages." (PMID 33328892, 2020).
type 1 diabetes (9 papers, 2011 to 2023). "Cerebral small-vessel disease (SVD) is prevalent in type 1 diabetes and has been associated with the haptoglobin variant allele Hp1." (PMID 36856861, 2023). "Another tubular injury marker is N-acetyl-β-D-glucosaminidase (NAG) which has been linked with DN in patients with type-1 diabetes (T1D), while haptoglobin emerged as a strong predictor of DN in patients with T2D." (PMID 36712680, 2022). "Specifically, in patients with haptoglobin genotype-2 (Hp2-2), vitamin E has been shown to be associated with an approximately 35% reduction in cardiovascular diseases in both type 1 diabetes and type 2 diabetes." (PMID 31885827, 2019). "Simpson and colleagues found that the HP genotype may help predict the rate of progression of coronary atherosclerosis in patients with type 1 diabetes." (PMID 34631895, 2021). "In addition, decreased RCT in type 1 diabetes was shown to be modified by the haptoglobin genotype with the haptoglobin 2-2 genotype resulting in an aggravated reduction." (PMID 22458435, 2012). "In addition our proteomic profiling data in the kidney are consistent with previous reports using type 1 diabetic animal models showing that the expression of calbindin, integrin B1, kininogen 1, haptoglobin, and glutathione peroxidase 1 are altered by the diabetic state." (PMID 29121074, 2017).